LINC-PINT (long independently transcribed non-coding RNA, p53 induced transcript)
Diseases named in the same sentence as LINC-PINT in open-access papers (continued):
Sharing a sentence is not in itself a finding about the gene and the disease.
cancer (36 papers, 2013 to 2025). A tumor composed of atypical neoplastic, often pleomorphic cells that invade other tissues. "The pooled analysis demonstrated a significant association between upregulation of LINC-PINT expression and better survival (P = 0.002) during the cancers." (PMID 38553526, 2024). "In our meta-analysis, we observed a significant association between elevated LINC-PINT expression and improved OS in cancer patients." (PMID 38553526, 2024). "Collectively, current evidence suggests LINC-PINT can be considered for use as a diagnostic/prognostic marker for cancer and several other diseases." (PMID 37006616, 2023). "Here we show how LINC-PINT, which is kept at low levels in tumors, acts as an inhibitor of this major cancer hallmark." (PMID 29078818, 2017). "However, it is noteworthy that certain investigations have reported that elevated LINC-PINT expression is associated with a better prognosis in cancer patients." (PMID 38553526, 2024). "Other replication studies could causally link mutations affecting lncRNAs, such as RMRP, NEAT1, or LINC-PINT, to cancer." (PMID 33329688, 2020). "Collectively, these findings underscore the significant role of LINC-PINT in the physiological and pathological processes of cancer." (PMID 38553526, 2024). "To shed light on this intriguing question, we have undertaken a comprehensive investigation that entails meta-analysis and bioinformatics analysis, aiming to elucidate the clinical significance and oncogenic mechanisms of LINC-PINT in the context of cancer." (PMID 38553526, 2024). "Remarkably, the results obtained from these subgroup analyses consistently supported the robust predictive value of LINC-PINT for OS in cancer patients, as it remained unaltered and consistent across the subgroups." (PMID 38553526, 2024). "Bioinformatics analyses further demonstrated that elevated LINC-PINT expression correlates with longer predicted survival in certain cancers such as BLCA, LUAD, PAAD, SARC, and SKCM." (PMID 38553526, 2024). "Although our results were limited by sample size, they still provided preliminary insights into the potential role of LINC-PINT in the prognosis of cancer patients." (PMID 38553526, 2024). "Our investigation unveiled a myriad of roles that LINC-PINT assumes in influencing OS within diverse cancer types." (PMID 38553526, 2024). "A systematic search was conducted in PubMed, Embase, Cochrane Library, and Web of Science databases to identify pertinent studies exploring the correlation between LINC-PINT expression and cancer patients." (PMID 38553526, 2024). "This study aims to comprehensively investigate the prognostic significance of LINC-PINT in diverse human cancer." (PMID 38553526, 2024). "While this study provides a comprehensive understanding of the clinical prognosis and oncogenic mechanisms of LINC-PINT in cancer, there are also several limitations that should be acknowledged." (PMID 38553526, 2024). "Overall, these findings indicate that LINC-PINT holds not only the potential to serve as a reliable clinical biomarker for cancer diagnosis and prognosis but also as a promising target for precision therapeutic interventions." (PMID 38553526, 2024). "LINC-PINT exerts an oncosuppressive role, although the molecular mechanism varies from cancer type to cancer type." (PMID 39054345, 2024). "Based on these facets, LINC-PINT emerges as a priority target for studying the clinical potential of lncRNAs (PINTology), especially for cancer therapeutics." (PMID 37006616, 2023). "LINC-PINT contributes to a variety of biological processes impacting cancer cell growth and metastasis, with involvement in processes ranging from DNA damage responses to cell senescence and apoptosis." (PMID 37006616, 2023).
cancer (continued). "The Cancer Genome Atlas (TCGA) was used to extract data regarding the expression of LINC-PINT, which was found to be significantly downregulated in cancer tissues compared with normal tissues." (PMID 36091809, 2022). "Metastasis, which is a primary factor in cancer progression, was significantly associated with BACE1 and LINC-PINT expression." (PMID 36087249, 2022). "Deregulation of linc-PINT plays an essential role in the pathogenesis of various cancer types, including acute lymphoblastic leukemia." (PMID 33805687, 2021). "This study was adopted to understand the roles and possible mechanisms of LINC-PINT in cancer development with regard to the regulation of ZEB1 expression." (PMID 34257531, 2021). "We further identified a functional role of LINC-PINT in inhibiting the malignant phenotypes and sensitizing cancer cells to irradiation in vitro and in vivo." (PMID 33963177, 2021). "The upregulation of ZEB1 expression was revealed to partly reverse the suppressive effects of LINC-PINT overexpression on cancer cell proliferation, invasion and migration abilities." (PMID 34257531, 2021). "Overall, these data supported that overexpression of LINC-PINT suppressed cancer development in vitro." (PMID 34257531, 2021). "To investigate the role of EZH2 in LINC-PINT regulating cancer development, we measured the impact of LINC-PINT on EZH2 expression." (PMID 34257531, 2021). "Ectopic expression of LINC-PINT inhibited cell proliferation and increased the S phase population in both cancer cells prominently." (PMID 33963177, 2021). "To further illuminate the underlying mechanism by which LINC-PINT regulates cancer development, we investigated the target genes of LINC-PINT." (PMID 34257531, 2021). "We selected 74 and 5 target mRNAs for HEIH and LINC-PINT, respectively, among which were those involved in important roles in cancer progression." (PMID 31098301, 2019). "Collectively our data show that LINC-PINT regulates the expression of genes that contribute to the ability of cancer cells to migrate, inducing the subcellular translocation of beta-catenin." (PMID 29078818, 2017). "Our data show that a truncated version of LINC-PINT (HCR) contains all the elements necessary to inhibit the migration of cancer cells." (PMID 29078818, 2017). "Interestingly, lincPINT expression is downregulated significantly in a variety of cancers including LUAD." (PMID 39062685, 2024). "These intriguing findings collectively indicate that LINC-PINT may hold promising potential as a prognostic biomarker for cancer patients, with its predictive value being partly contingent on the particular cancer type under consideration." (PMID 38553526, 2024). "Other positive associations with neuropathy along with pemphigus foliaceous, diabetes, and arthritis may also be exploited, suggesting LINC-PINT as a multifaceted target for cancers and other diseases." (PMID 37006616, 2023). "Similarly, LINC-PINT is a crucial lncRNA that mainly acts as an onco-suppressor in various cancers, but its clinical use is almost neglected." (PMID 37006616, 2023). "Furthermore, some of these are cancer treatments with inhibitors of LINC-PINT’s targets now being used in treating melanoma." (PMID 37006616, 2023).
cancer (continued). "It would be similarly valuable to ascertain more knowledge of the natural activators or inhibitors of LINC-PINT, which could be used to open potential new doors in cancer therapeutics." (PMID 37006616, 2023). "The significant role of LINC-PINT in cancers has been well illustrated." (PMID 34257531, 2021). "Here, this study aims to disclose the role of LINC-PINT in cancer development, which may contribute to improving the clinical outcomes of LSCC treatment." (PMID 34257531, 2021). "Here we characterize the function of the human lncRNA LINC-PINT in cancer." (PMID 29078818, 2017). "The gain of function of LINC-PINT has a strong impact on the invasive capacity of cancer cells." (PMID 29078818, 2017). "Among the 19 TSLNRs in this study, only eight (EPB41L4A-AS2, MEG3, LINC-PINT, FTX, HCG11, HAND2-AS1, SNHG5 and TPT1-AS1) have been reported previously to be associated with malignancy, and the potential functions of the other 11 lncRNAs in human cancer remain a mystery." (PMID 30764831, 2019). "Thus, the prospect of LINC-PINT serving as a pan-cancer biomarker remains unknown." (PMID 38553526, 2024). "Across the majority of cancer investigated, heightened expression of LINC-PINT was consistently correlated with extended OS periods, a compelling observation indicative of its potential beneficial role in these contexts." (PMID 38553526, 2024). "LncRNAs have been shown to be expressed in all major cancer types, contribute to the hallmarks of cancer, and can act as oncogenes (“onco-lncRNAs”, such as HOTAIR, NEAT1 and MALAT1) or tumor suppressors (e.g. GAS5, MEG3, NBAT and LINC-PINT)." (PMID 37346034, 2023). "Altered expression of lncRNAs, such as PTENP1, linc-PINT, and GAS5, plays an essential role in regulating apoptosis in cancer cells." (PMID 33805687, 2021). "Given the literature on LINC‐PINT function, these results suggest that the LINC‐PINT/PRC2 interaction, identified in cancer, is also relevant in the context of brain and neurodegeneration." (PMID 32080970, 2020). "The cancer-specific roles of these mRNAs suggest the potential importance of HEIH and LINC-PINT in EOC." (PMID 31098301, 2019). "We then confirmed that LINC-PINT and PRC2 interact in human cells of different origins, including normal and cancer cell lines, by detecting specific enrichment of LINC-PINT in PRC2 immunoprecipitates, as well as the reciprocal RNA pulldown experiments." (PMID 29078818, 2017). "In particular, the relationship between the functions of LINC-PINT in cancers versus non-malignant diseases needs to be better explored." (PMID 37006616, 2023).
LINC-PINT also shares sentences with these, for which no sentence is quoted: infection (5 papers); retinopathy (4); acute myocardial infarction (2); Alzheimer disease (2); colorectal tumors (2); prostate carcinoma (2); Adrenocortical Carcinoma (1); anaemia (1); anaplastic astrocytoma (1); bipolar disorder (1); bladder urothelial carcinoma (1); breast invasive carcinoma (1); cervical squamous cell carcinoma (1); dermatitis (1); diabetes (1); endocervical adenocarcinoma (1); kidney cancer (1); laryngeal squamous cell carcinoma (1); laryngeal tumors (1); lumbar disc herniation (1); myeloma (1); Nephropathy (1); pancreatic adenocarcinoma (1); pancreatic ductal adenocarcinoma (1); psychosis (1); rectum adenocarcinoma (1); renal carcinoma (1); sarcoma (1); schizophrenia (1); Skin Cutaneous Melanoma (1).
A further 4 diseases each share a sentence with LINC-PINT in 1 paper.